CD4 (CD4 molecule)
Diseases named in the same sentence as CD4 in open-access papers (continued):
Sharing a sentence is not in itself a finding about the gene and the disease.
AIDS (continued). "Some of them may die because of AIDS defining illness even before having the possibility to start ART, and individuals with very low CD4+ T cell count have a higher probability of developing complications on starting ART." (PMID 29970017, 2018). "We confirm previous reports that there are relatively subtle differences in fecal microbiome composition with HIV infection in the absence of CD4+ T cell counts indicative of AIDS, or when analyzing populations dominated by heterosexual transmission." (PMID 30396369, 2018). "Very late presenters (VLP) or patients with advanced HIV disease (AHD) are those with a CD4+ T-cell count below 200 cells/μl or AIDS, regardless of CD4+ T-cell count." (PMID 30587143, 2018). "A role of direct infection in loss of CD4 cells is also refuted by SIV infection in natural host where high levels of infection and viremia do not result in AIDS development." (PMID 28829402, 2017). "Exploring the association of alcohol use with CD4+ T-cell count among PLHIV in this setting has major implications on the HIV/AIDS care, treatment and ART monitoring in this setting as well as contribution to the global unanswered question of the effect of alcohol use on CD4+ T-cell count." (PMID 28665974, 2017). "In addition, the population in this study had relatively low nadir CD4+ count (<350 cells/mm3) and a worse WHO HIV/AIDS score III/IV (50%) hence more likely to have higher HPV prevalence." (PMID 29037188, 2017). "Visceral leishmaniasis is one of the AIDS-defining conditions, requiring anti-leishmanial treatment and cART irrespective of CD4+ T cell count." (PMID 29375567, 2017). "This suggests that CD4+ T-cell depletion and/or degree of immune activation do not consistently correlate with or promote disease progression to AIDS as has been shown with adult infections." (PMID 29259605, 2017). "In treatment-naïve patients starting on rilpivirine very few had an HIV-RNA >100 000 copies/ml at start of treatment confirming its use according to label, very few had low CD4 cell counts and none of the patients had an AIDS diagnosis." (PMID 28207816, 2017). "Other factors significantly associated with early CD4 T-cell recovery included a history of AIDS-defining illness, younger age, shorter duration on ART, higher log baseline viral load (time-dependent), higher baseline CD4 T-cell and higher CD8 T-cell counts (time-dependent)." (PMID 29016635, 2017). "Late presenter was defined as a person diagnosed with HIV with a CD4 cell count <350 cells/mm3 or an AIDS defining illness regardless of the CD4 cell count in the six months after HIV diagnosis." (PMID 29084276, 2017). "Since foreign aid for HIV/AIDS in Vietnam is rapidly decreasing, we sought to assess willingness to pay (WTP) for viral load and CD4 cell count tests among HIV-positive patients, and identified factors that might inform future co-payment schemes." (PMID 28199405, 2017). "In the setting of chronic HIV infection, clinical parameters such as CD4:CD8 ratio have been used to identify HIV+ individuals on ART who are at greater risk of immune dysfunction, leading to AIDS, non-AIDS events, and mortality." (PMID 28158203, 2017). "Male sex, CD4 cell count less than 200cells/μl, WHO stage of HIV/AIDS 3 & 4 and being non-employed were risk factors for TB incidence." (PMID 28049455, 2017). "For example, one study found that 21% of MSM who screened HIV-positive did not receive confirmatory testing and 34% of MSM newly diagnosed with HIV/AIDS did not receive CD4 testing within 12 months, posing significant challenges to the test-and-treat strategy." (PMID 28302106, 2017). "We keep the b = 3.5x10-5 and decrease the T ̄ number to i) T ̄ = 5x105 cells per ml, corresponding to average chronic HIV CD4+ T cell numbers; ii) T ̄ = 3.3x105 cells per ml as in the HIV/HPV co-infection study; and iii) T ̄ = 2x105 cells per ml, corresponding to AIDS." (PMID 28060843, 2017).
AIDS (continued). "‘HIV disclosure concerns’ were greater in individuals without an AIDS diagnosis in two studies, and greater in those with lower CD4 counts, no HIV-related hospitalisations, no partner, and of younger age in one study." (PMID 27406227, 2017). "In this article, we present the case of a 33-year-old AIDS patient with high viral load, CD4 lymphocyte count of 1/mm3, who presented with nonspecific symptoms, anemia, thrombocytopenia, and increased lactate dehydrogenase, alkaline phosphatase, and ferritin." (PMID 29164156, 2017). "In fact, increased inflammatory biomarkers are predictive of the development of non-AIDS conditions, independent of CD4+ T-cell count and HIV VL." (PMID 29209103, 2017). "In Ethiopia, factors such as severe anemia, a history of co-infection with tuberculosis (TB), marital status, WHO stage, low CD4 counts, poor adherence to ART, substance use, and opportunistic infections, were also found to be important determinants of HIV/AIDS-related deaths." (PMID 28287498, 2017). "The median CD4 cell count for a total of 543 participants (included 79 cases of progression to AIDS or death, but not 21 cases with missing data of CD4 cell count) significantly increased from 388/μL to 437/μL over this time." (PMID 28553428, 2017). "An interesting observation was that the ratio of CD4+/CD8+ in the peripheral blood of 12/16 RRP patients was inverted from the expected normal value >1–<1, a value commonly observed in HIV patients entering the AIDS phase of the disease." (PMID 28805308, 2017). "A distinct subgroup of HIV-1-infected individuals—termed viremic non-progressors (VNP) or controllers—do not seem to progress to AIDS, maintaining high CD4+ T cell counts despite high levels of viremia for many years." (PMID 28331526, 2017). "In his budget vote speech in July 2014, shortly after returning from the 20th International AIDS Conference in Melbourne Australia, South Africa’s Minister of Health endorsed the 90–90–90 targets and treatment irrespective of CD4 count." (PMID 39450053, 2017). "Some clinical studies have shown that herbal medicines might have the potential to alleviate symptoms, reduce viral load, and increase CD4+ cells for HIV-infected individuals and AIDS patients." (PMID 28603710, 2017). "Moreover, several studies have found that LTNPs display a higher level of HIV-specific CD4+ and CD8+ T cell responses than that in chronic progressors, which greatly slows disease progression to AIDS." (PMID 28222782, 2017). "The CD4 count measured at ART start loses its predictive value as duration of ART increases, whereas CD4:CD8 ratio has, at least in some studies, been found to predict non-AIDS morbidity and mortality after long-term ART." (PMID 28903507, 2017). "HIV-1, and its simian counterpart, SIV, infect and kill CD4 T cells, resulting in their massive depletion that ultimately leads to AIDS in the absence of antiretroviral therapy." (PMID 28654687, 2017). "Late presenter with advanced disease was defined as a person diagnosed with HIV with a CD4 cell count <200 cells/mm3 or an AIDS defining illness, regardless of CD4 cell count in the six months after HIV diagnosis." (PMID 29084276, 2017). "Prognostic factors associated with death without NAE were older age, lower CD4 cell count and higher HIV viral load both at cohort engagement, AIDS diagnosis at cohort entry and hepatitis C virus coinfection." (PMID 28886092, 2017). "Some clinical studies show that herbal medicines might have the potential to alleviate symptoms, reduce viral load, and increase CD4+ cells for HIV-infected individuals and AIDS patients." (PMID 28603710, 2017). "Scores were +3.5 for age <30 years, +2.5 for BMI of 18.5–29.9 kg/m2 or +14.5 for BMI of >30 kg/m2, +7.0 for non-anemia, +17.0 for CD4 count >200 cells/mm3 or +5.5 for 100–199 cells/mm3, and +8.5 for no prior AIDS-defining illness." (PMID 28484509, 2017).
AIDS (continued). "By definition, immunity against HIV via epigenetic responses, also known as epigenetic immunity, is also heritable, shown by the memory CD4 T-cell responses against HIV in elite controllers, posttreatment controllers, and patients with AIDS in spite of shown different degrees of anti-HIV immunity." (PMID 28497113, 2017). "The initial multivariable model included CD4+ T-cell count at enrollment, sex, cigarette smoking, co-trimoxazole adherence level, CESD category, duration since testing HIV positive and the WHO HIV/AIDS clinical diseases stage." (PMID 28665974, 2017). "We further investigated the possibility of HPV persistence and found that weak cART or AIDS level CD4+ T cells, which do not rebound to high enough levels, are needed for HPV to remain chronic following cART." (PMID 28060843, 2017). "Data were then stratified by the presence of a concurrent AIDS diagnosis and, for people without concurrent AIDS, by CD4 cell count levels at the time of diagnosis i.e. ≥ 500, 350–499, 200–349, < 200 cells/mm3." (PMID 29208159, 2017). "Late diagnosis refers to people with HIV with a CD4 count below 350 cells/ul, or having an AIDS-defining event regardless of the CD4 count." (PMID 28270139, 2017). "In comparison with people without hyponatremia, those with hyponatremia had significantly more severe HIV disease with a lower CD4 cell count (208 ± 198/μl vs 400.4 ± 277/μl), about twice the HIV viral load and an approximatively four-fold higher prevalence of AIDS." (PMID 28122494, 2017). "There was little evidence that CD4:CD8 ratio or CD8 count was independently prognostic for non-AIDS mortality." (PMID 28903507, 2017). "None of the HIV controllers exhibited AIDS-related conditions and the CD4+ T cell counts were ≥500 cells/μL during follow-up." (PMID 28464889, 2017). "Viremic non-progressor (controller) patients do not progress to AIDS, maintaining high CD4+ T-cell counts with HIV-1 replication for many years." (PMID 28331526, 2017). "We found that the ART coverage before the Ebola outbreak and the probabilities of dying with and without undergoing ART for persons with a CD4 count <200 cells/mm3 were of most value in determining additional HIV/AIDS deaths attributable to Ebola." (PMID 26886846, 2016). "This study clearly shows that low CD4+ T cell count appeared to be a risk factor for infection with intestinal parasites and the development of diarrhea in HIV/AIDS irrespective of the ART status." (PMID 26754404, 2016). "According to the consensus, late presentation was defined as persons presenting for care with a CD4 cell count below 350 cells/μL or presenting with an AIDS-defining event, regardless of the CD4 cell count." (PMID 27761466, 2016). "Though the difference was not statistically significant, the mean CD4 cell count (Mean + SD) for HBV-HIV/AIDS co-infection (320 + 126 cells/μl) was lower than HIV/AIDS alone (402 + 201 cells/μl)." (PMID 26855663, 2016). "Among the HIV+ participants, men had a longer cumulative duration of NRTI and NNRTI therapy but a shorter duration of PI therapy compared with women; the HIV+ men had higher CD4+ and CD8+ cell counts; and the HIV+ women had a higher proportion of clinical AIDS." (PMID 28217403, 2016). "The WHO 2016 guidelines recommend providing lifelong ART to all HIV patients regardless of CD4 cell count but the monitoring of drug resistant HIV-1 is still a challenge to control the HIV/AIDS epidemic." (PMID 27798676, 2016). "Although Nef is not essential for virus replication in vitro, humans infected with Nef-deficient HIV-1 display greatly reduced viral titers, maintain higher CD4+ T cell counts and generally do not progress to AIDS." (PMID 26950141, 2016). "Studies of HLA and killer-cell immunoglobulin-like receptors revealed that individuals expressing KIR2DS2 have a more rapidly declining CD4 population and progression to AIDS than those who do not." (PMID 28050553, 2016).
AIDS (continued). "Interestingly, AIDS-BL, was shown to be very common among HIV-infected individuals with a wide range of CD4 counts, and usually appears as one of the symptoms of AIDS with 30–40% of these BL-tumors are positive for EBV." (PMID 27826287, 2016). "A CD4-PE molecule was have been intensively studied and used to treat AIDS in clinical trials in the 1990s without efficacy." (PMID 27049645, 2016). "In the present study, we defined late diagnosis as a CD4-positive T lymphocyte count <350 cells/mm3 and very late diagnosis as a count <200 cells/mm3 at diagnosis, excluding AIDS-defining illness, regardless of the CD4 cell count." (PMID 26934235, 2016). "However, its high supply and maintenance costs inspired the Senegalese AIDS National Program and the Army AIDS Program to progressively switch toward affordable new POC CD4 counting instrument including the PIMATM Alere which is able to respond to this demand." (PMID 27166955, 2016). "In 2014, 44% of newly diagnosed persons presented late for care (CD4 count < 350 cells/mm3 or with an AIDS-defining event regardless of CD4 count)." (PMID 27855639, 2016). "We used a consensus definition of advanced HIV, part of which is based upon presenting with an AIDS-defining event regardless of CD4 count." (PMID 27091128, 2016). "In multivariable Cox analyses, CCASAnet patients had a higher hazard of mortality after ART initiation (adjusted hazard ratio (AHR) 1.61; 95% CI: 1.32 to 1.96), adjusting for age, sex, CD4 count, year of ART initiation, intravenous drug use, prior AIDS diagnosis and ART regimen." (PMID 26996992, 2016). "Raising the CD4 threshold to 500/mm3 is based on high-quality evidence from HPTN052 that ART reduces HIV transmission, but low-quality evidence from cohort studies that ART reduces mortality or progression to AIDS." (PMID 27462361, 2016). "All six patients had worsening immunological control (mean CD4 count: 97 cells/mm3, range: 0–177 cells/mm3); however, there were no AIDS events over the 24 months of follow-up." (PMID 26661398, 2016). "The recent TEMPRANO and START trials demonstrated that AIDS and non-AIDS events can occur even in patients with high CD4 counts (>500/mm3)." (PMID 27509048, 2016). "As recommended by the government, treatment of HIV/AIDS in Yaounde and Cameroon as a whole commences at diagnosis and not dependent on the CD4+ T cell count as it was before." (PMID 27619013, 2016). "In practice, a substantial number of HIV-positive persons diagnosed soon after seroconversion initiate cART immediately, even without having a low CD4+ cell count (i.e. with >500 CD4+ cells/μl), or AIDS-related conditions." (PMID 26636925, 2016). "In contrast to other migrant groups, Eastern European migrants present to care at an earlier stage of HIV-infection than non-migrants in terms of AIDS and mean CD4-count." (PMID 27927190, 2016). "In order to allow regular access to CD4+ T cell enumeration of military personnel as well as their dependents and civilians living with HIV, the Senegalese Army AIDS program is implementing PIMATM Alere technology in urban and semi-urban military medical centres." (PMID 27166955, 2016). "We compared time trends for percentage of AIDS (CDC Stage C) and mean CD4-count at enrolment between migrants from Western Europe (WE), Central Europe (CE), Eastern Europe (EE), Sub-Saharan Africa (SSA), South East Asia (SEA) and non-migrants using multivariable regressions." (PMID 27927190, 2016). "Some HIV-infected patients were not identified until their CD4 counts decreased to less than 200 cells/mm3, after the onset of AIDS." (PMID 26883427, 2016). "The percentage of CD4+ and CD8+ subpopulations was affected by HIV/AIDS, as expected." (PMID 27382604, 2016). "Inclusion criteria were a CD4 count above 300 cells/μl, the absence of AIDS-defining symptoms and an ART-naïve therapy status." (PMID 26812052, 2016).
AIDS (continued). "Presentation with advanced HIV disease was defined as persons presenting for care with a CD4 cell count below 200 cells/μL or presenting with an AIDS-defining event, regardless of the CD4 cell count." (PMID 27761466, 2016). "Identifying predictors of CD4 reconstitution during cART is clinically important since the rate of both AIDS and serious non-AIDS events decrease at higher CD4 counts, even among the subgroup of individuals with CD4 counts >500 cells/mm3." (PMID 25928043, 2015). "If implementing early ART initiation within the current care continuum, we estimated 1,050,000 new HIV infections (95% 706,000–1,729,000) and 883,000 AIDS-related deaths over two decades, or 18 and 9% reductions (respectively) compared to ART initiation at CD4 ≤350 cells/mm3." (PMID 26434780, 2015). "Prognosis of CMV EOD was poor as indicated by higher death rates among subjects with lower CD4 count, and specific cut-off values were found to have useful potential for identification and treatment of CMV infected HIV/AIDS patients in due time to avoid CMV EODs among HIV/AIDS subjects." (PMID 25679798, 2015). "Although all patients had a confirmed AIDS (clinical) diagnosis, there were no information respecting 29.5% of the CD4 counts and 42.5% HIV-1 RNA viral load determinations in the merged database." (PMID 25886530, 2015). "Neither sex, a CD4+ cell count in the range 200 to 350 cells/μL nor prior AIDS-defining events influenced the likelihood of adequate CD4+ cell count and viral load monitoring." (PMID 26478610, 2015). "HIV long-term nonprogressors (LTNP) are characterized by long periods (>10 years) of AIDS-free symptoms even without antiretroviral treatment and maintain low levels of viremia and elevated CD4+ T cells counts." (PMID 26568963, 2015). "No AIDS-defining opportunistic infections were diagnosed when the CD4 count was less than 200 cells/mm3." (PMID 26268903, 2015). "In our study population cohort, comprising of 400 late diagnosed [mean baseline CD4+ cell count being 45 (range 4–100) at the time of their HIV-1 diagnosis and recruitment for the study] HAART naïve HIV/AIDS patients, 40.5% (162/400) subjects were diagnosed with different stages of CMV disease." (PMID 25679798, 2015). "Therefore, our microarray results were further confirmed in the CD4+ T lymphocyte cell line and recruited HIV/AIDS patients." (PMID 26039376, 2015). "As a result of the loss of CD4+ T cells, HIV/AIDS patients without antiretroviral therapy (ART) are highly susceptible to infections by different microbes in the natural environment." (PMID 26540050, 2015). "As of 2013, WHO and UNAIDS recommend treatment initiation when CD4 <500 cells/mm3 or with an AIDS-defining event, regardless of CD4 count at the time of treatment initiation." (PMID 25735869, 2015). "Another study showed that common lesions in HIV/AIDS patients (including hairy leukoplakia, necrotizing ulcerative periodontitis, xerostomia, Kaposi sarcoma, HSV, and major aphthous ulcers) were concurrent with a decrease in CD4+ count." (PMID 25745611, 2015). "Antiretroviral-naïve HIV-1-infected individuals newly enrolled in the FHDH cohort between 2002–2010, with CD4 cell counts &gt;200/μL and no previous or current AIDS events were included." (PMID 25734445, 2015). "Male gender, year of enrolment before 1993, older age at enrolment, intravenous drug use, low CD4 cell count, AIDS event, cancer occurrence and the absence of antiretroviral therapy were all associated independently with risk of death." (PMID 25884678, 2015). "CD4 T cell activation, through either HIV-1 gp120 or IL-7, renders CD4 T cells prone to Fas-mediated apoptosis through ezrin-Fas linkage and therefore to apoptosis of bystander uninfected T cells in AIDS patients." (PMID 26010871, 2015). "Vaccine responses were dependent on age, the presence of an AIDS-defining illness, CD4 count and HIV viral load, although none of these factors were consistently predictive of poorer antibody responses." (PMID 26654248, 2015).